ZSWIM7 (zinc finger SWIM-type containing 7)
Description:
Involved in early stages DNA double-strand break (DSB) repair via homologous recombination (HR). Forms a heterodimeric complex with ZSWIM7/SWS1 that promotes HR by regulating replication protein-A (RPA) dynamics on single-stranded DNA, thereby stabilizing RAD51 and DMC1 filaments on DNA. The SWSAP1-ZSWIM7/SWS1 heterodimer is essential during meiosis by stabilizing DMC1 filaments. In contrast, it is critical for only certain types of homologous-directed DNA repair, such as inter-homolog homologous recombination (IR-HR). IR-HR is a DNA repair mechanism where a cell repairs a DSB on one chromosome using the matching homologous chromosome as a template, rather than the sister chromatid.
Synonyms: SWS1; ODG10; SPGF71
Tractability: PROTAC: ubiquitination databases record sites on it.
Gene: Protein-coding gene on chromosome 17 (15,976,560 to 15,999,717, reverse strand). Ensembl gene ENSG00000214941.
Subcellular location: Chromosome; Nucleus
Subcellular location (Human Protein Atlas): Cytosol
Gene Ontology:
Molecular function: protein binding; zinc ion binding
Biological process: DNA recombinase assembly; double-strand break repair via homologous recombination; protein stabilization; double-strand break repair involved in meiotic recombination
Cellular component: Shu complex; chromosome; nucleus
Genetic constraint (gnomAD): Loss-of-function variants: 12 observed, 11.99 expected, observed/expected ratio (o/e) 1, 90% interval 0.64 to 1.6. The upper end of that interval is the gene's LOEUF score, 1.6, which puts it in group 6 of 6, group 1 being the genes least tolerant of losing a copy. Missense variants: 174 observed, 150.31 expected, observed/expected ratio (o/e) 1.16, 90% interval 1.02 to 1.31. Synonymous variants: 60 observed, 60.87 expected, observed/expected ratio (o/e) 0.99, 90% interval 0.8 to 1.22.
Homologues: Orthologues: chimpanzee ZSWIM7 (99% identical), macaque ZSWIM7 (99% identical), rabbit ZSWIM7 (89% identical), guinea pig ZSWIM7 (86% identical), dog ZSWIM7 (86% identical), rat Zswim7 (85% identical), pig ZSWIM7 (84% identical), mouse Zswim7 (81% identical), tropical clawed frog zswim7 (59% identical), zebrafish zswim7 (53% identical).
Diseases named in the same sentence as ZSWIM7 in open-access papers:
ZSWIM7 is named in the same sentence as 10 diseases in open-access papers, as found by Europe PMC text mining. Sharing a sentence is not in itself a finding about the gene and the disease. The quoted sentences say what the papers report.
male infertility (3 papers, 2022 to 2023). The inability of the male to effect fertilization of an ovum after a specified period of unprotected intercourse. "Recently, a homozygous splice variant (c.201 + 1G > T) and a homozygous frameshift variant (c.231_232del; p.(Cys78Phefs*21)) in ZSWIM7 itself have been shown to be associated with human male infertility in 4 unrelated patients." (PMID 34402903, 2022). "Recurrent ZSWIM7 (zinc finger SWIM-type containing 7) mutations lead to human male infertility." (PMID 36766254, 2023). "MRPL50 could therefore be considered a candidate gene underlying male infertility, consistent with many known POI genes that can cause infertility of both sexes (e.g. STAG3, ZSWIM7, etc.)." (PMID 37148394, 2023).
Infertility (2 papers, 2022 to 2023). "Zswim7 (Sws1)/Swsap1 mutant mice reproduce the infertility phenotype, demonstrating marked meiotic abnormalities." (PMID 34402903, 2022). "Our association of ZSWIM7 with POI suggests that disruption of this gene can result in both POI and male factor infertility, which has important clinical implications when counseling patients and their families." (PMID 34402903, 2022).
Azoospermia (1 paper, 2022). Absence of any measurable level of sperm,whereby spermatozoa cannot be observed even after centrifugation of the semen pellet. "Several homologous recombination genes have been implicated in the pathogenesis of POI and azoospermia, including some which are postulated to interact with ZSWIM7." (PMID 34402903, 2022).
COVID-19 (1 paper, 2024). A disease caused by infection with severe acute respiratory syndrome coronavirus 2. "Apart from this, ZSWIM7 was the most common gene seen between BMI and critical COVID-19, which was found in 12 tissues." (PMID 38352709, 2024).
cutaneous melanoma (1 paper, 2019). A primary melanoma arising from atypical melanocytes in the skin. "Our study also proposes genes ESM1, NFATC3, C7orf4, CDK14, ZNF827, and ZSWIM7 as novel putative markers for cutaneous melanoma metastasis." (PMID 31673075, 2019).
ovarian dysgenesis (1 paper, 2023). "The 17p12 region has been previously associated with ovarian dysgenesis (OMIM #619834) due to homozygous mutations in the ZSWIM7 gene." (PMID 37202802, 2023).
cancer (2 papers, 2022 to 2023). A tumor composed of atypical neoplastic, often pleomorphic cells that invade other tissues. "MtrBTN2 cancer was found to express at higher levels a significant panel of transcripts of genes involved in the DNA homologous recombination (HR) (42.Double-strand break repair), such as BABAM1, ZSWIM7, RAD51L, RAD54L, MRE11, MCM9 and TONSL." (PMID 37816387, 2023).
ZSWIM7 also shares sentences with these, for which no sentence is quoted: Meiosis (1 paper); ovarian insufficiency (1); Parkinson disease (1).